ZNF250 (zinc finger protein 250)
Description:
May be involved in transcriptional regulation.
Synonyms: ZNF647; MGC9718; ZFP647
Tractability: PROTAC: UniProt records ubiquitination sites on it; ubiquitination databases record sites on it.
Gene: Protein-coding gene on chromosome 8 (144,876,497 to 144,902,217, reverse strand). Ensembl gene ENSG00000196150.
Subcellular location: Nucleus
Subcellular location (Human Protein Atlas): Nuclear speckles; Cytosol
Pathways (Reactome):
Gene expression (Transcription): Generic Transcription Pathway
Gene Ontology:
Molecular function: sequence-specific double-stranded DNA binding; DNA-binding transcription factor activity, RNA polymerase II-specific; RNA polymerase II cis-regulatory region sequence-specific DNA binding
Biological process: regulation of transcription by RNA polymerase II; regulation of DNA-templated transcription
Cellular component: nucleus
Genetic constraint (gnomAD): Loss-of-function variants: 15 observed, 43.53 expected, observed/expected ratio (o/e) 0.34, 90% interval 0.23 to 0.53. The upper end of that interval is the gene's LOEUF score, 0.53, which puts it in group 2 of 6, group 1 being the genes least tolerant of losing a copy. Missense variants: 474 observed, 726.15 expected, observed/expected ratio (o/e) 0.65, 90% interval 0.61 to 0.7. Synonymous variants: 251 observed, 276.9 expected, observed/expected ratio (o/e) 0.91, 90% interval 0.82 to 1.01.
Homologues: Orthologues: chimpanzee ZNF250 (99% identical), macaque ZNF250 (98% identical), rabbit ZNF250 (87% identical), guinea pig ZNF250 (86% identical), rat Zfp647 (84% identical), mouse Zfp647 (83% identical), dog ZNF250 (80% identical), pig ZNF250 (79% identical). Paralogues in human: ZNF41 (49% identical), ZNF484 (49% identical), ZNF33B (48% identical), ZNF568 (48% identical), ZNF658 (48% identical), ZNF182 (47% identical), ZNF189 (47% identical), ZNF7 (47% identical), ZNF16 (47% identical), ZNF879 (47% identical), ZNF708 (46% identical), ZNF235 (46% identical), and 164 more.
Diseases named in the same sentence as ZNF250 in open-access papers:
ZNF250 is named in the same sentence as 4 diseases in open-access papers, as found by Europe PMC text mining. Sharing a sentence is not in itself a finding about the gene and the disease. The quoted sentences say what the papers report.
breast carcinoma (2 papers, 2021). "ZNF250 overexpression significantly predicted reduced survival of TCGA breast cancer patients." (PMID 34638319, 2021).
tumor (5 papers, 2018 to 2025). "The ZNF (Zinc Finger) family includes TFs such as ZNF18 and ZNF250, which are involved in gene regulation and modulation of tumor cell behavior." (PMID 41155227, 2025). "Here, we demonstrate that the overexpression of ZNF250, ZNF324B, and ZNF331 is significantly negatively associated with tumor dedifferentiation status and that higher-grade tumors (with cancer stemness characteristics) express substantially lower levels of those transcription factors." (PMID 34638319, 2021).
infection (1 paper, 2021). The state of being infected such as from the introduction of a foreign agent such as serum, vaccine, antigenic substance or organism. "NFE2L2 (Nuclear Factor Erythroid 2-Like 2; OMIM 600492), ZNF250 (Zinc Finger Protein 250) and ZNF549 (Zinc Finger Protein 549) were activated in response to infection (i.e., Herpes Simplex Virus) and inflammation." (PMID 33466592, 2021).
ZNF250 also shares sentences with these, for which no sentence is quoted: cancer (2 papers).